IGF1 (insulin like growth factor 1)
Diseases named in the same sentence as IGF1 in open-access papers (continued):
Sharing a sentence is not in itself a finding about the gene and the disease.
prostate carcinoma (continued). "There is evidence that vitamin D may increase levels of IGF-1 in healthy individuals, and increased levels of IGF-1 in serum have been correlated with increased prostate cancer risk." (PMID 28417914, 2017). "Circulating IGF-1 has been associated with increased risk of advanced prostate cancer, and binding proteins may be associated with prostate cancer development or progression." (PMID 28417914, 2017). "In addition, GH/IGF1 axis is an important regulatory system for prostatic disorders 4, and its alterations have been linked to prostate cancer development." (PMID 28244645, 2017). "In addition, evidence from population-based screening cohorts has demonstrated that both insulin and IGF-1 levels correlate more closely than PSA levels with the risk of developing prostate cancer." (PMID 27599544, 2016). "Height at 13 years may be a biological marker for an increased level of insulin-like growth factor 1, which is especially high during puberty and is associated with an increased risk of prostate cancer." (PMID 26951518, 2016). "Finally, elevated circulating levels of IGF-1, leptin and adiponectin, commonly encountered in MetS patients, have all been associated with prostate cancer risk." (PMID 27386844, 2016). "Elevated IGF-1 levels are seen as a risk factor for prostate cancer 45–46." (PMID 23668396, 2014). "GH and IGF1 levels decline with aging, concordant with loss of muscle and bone mass and an increase in fat deposition and BMI, and selected studies have reported an association between prostate cancer and blood IGF1 or genetic variants in IGF1 or IGFBP3." (PMID 22257467, 2012). "IGF-1 blood levels are positively associated with increased risk of advanced stage prostate cancer." (PMID 23272133, 2012). "Since IGF binding protein 1 controls the amount of IGF-1 free levels, less circulating insulin may indirectly mitigate prostate cancer risk." (PMID 21773024, 2011). "IGF-1 levels have been associated with increased prostate cancer risk." (PMID 21773024, 2011). "Statistically significant associations between IGF-1 and colorectal and prostate cancer may also be of aetiological significance, but the evidence is weaker." (PMID 16804529, 2006). "The odds ratio of prostate cancer in the highest quartile compared with the lowest quartile was very high (OR=31 95% CI: 10–92), demonstrating by comparison the modest association with IGF-1, in spite of it being statistically significant." (PMID 16804529, 2006). "While some authors postulated that dairy protein is positively associated with increased IGF-1 levels, which may stimulate the initiation and progression of prostate cancer, others assumed the amount of dietary calcium and fat content to be relevant in the disease process." (PMID 39954205, 2025). "In our study, elevated levels of insulin and IGF-1 in the PCa-DM group are positively correlated with the prostate cancer grade and risk, supporting the hypothesis that the mitogenic and oncogenic roles of insulin and IGF-1 might be associated with cancer aggressiveness in the diabetic group." (PMID 41367482, 2025). "Therefore, IGF-1 increases prostate cancer risk by reducing SHBG levels." (PMID 39781351, 2025). "Thus, the variations in the IGF-1 system might underlie associations of height with prostate cancers that are more likely to progress." (PMID 38489391, 2024). "Our study had small sample size, thus may not be generalized to other ethnicities; hence, multicenter studies examining the association of lipid profile and serum insulin, insulin-like growth factor-1 levels with benign prostatic hyperplasia or prostate cancer are warranted." (PMID 39781138, 2024). "Besides, high intake of dietary fiber in healthy plant-based diets could reduce the risk of prostate cancer by improving insulin sensitivity and reducing the bioavailability of insulin-like growth factor-1 (IGF-1)." (PMID 38902815, 2024).
prostate carcinoma (continued). "In vivo and in vitro models for prostate cancer suggest that diets containing walnuts and almonds may reduce the risk of prostate cancer through declines in plasma levels of IGF-1, resistin, LDL-cholesterol, oxidative stress, and inflammation, and increased expression of tumor suppressors." (PMID 36986173, 2023). "A study of the association between dietary protein and risk of prostate cancer in the NCI Breast and Prostate Cancer Cohort Consortium (BPC3) a high intake of dairy protein may increase prostate cancer risk by increasing the production of insulin-like growth factor 1 (IGF-1, 21]." (PMID 32359345, 2020). "Moreover, a growth factor structurally similar to insulin peptide, called Insulin Like Growth factor type 1 (IGF-1), is inversely associated with all-cause mortality in men affected by prostate cancer if fact it is a candidate prognostic marker in patients affected by advanced disease." (PMID 28389628, 2017). "Additionally, higher intakes of milk and calcium may increase insulin-like growth factor-1 (IGF-1), which may be associated with increased prostate cancer risk." (PMID 17106437, 2006). "This study evaluated the epidemiological evidence for serum insulin-like growth factor-1 (IGF-I) levels and the risk of prostate cancer, and the results indicate that high serum IGF-I levels are associated with an increased risk of prostate cancer." (PMID 41584612, 2025). "In PC3 cell lines, a human prostate cancer model commonly used to study hormonal signalling pathways, E2 modulates the expression of IGF1-Ea and IGF1-Eb while concurrently downregulating IGF1-Ec." (PMID 39796756, 2025). "Elevated insulin-like growth factor-1 (IGF-1), for instance, has been associated with increased prostate cancer risk." (PMID 40852019, 2025). "IGF-1 accelerated the growth of prostate cancer by activating phosphoinositide 3-kinase and mitogen-activated protein kinase or increasing sex hormone sensitivity." (PMID 39941741, 2025). "Insulin-like growth factor (IGF)-1 and its binding proteins are important in cancer growth, especially in prostate cancer." (PMID 39941741, 2025). "This dysbiosis regulated insulin-like growth factor-1 (IGF-1) through SCFAs, promoting the proliferation of prostate cancer cells." (PMID 40401130, 2025). "Although originating from prostate cancer, this model offers valuable insights into oestrogen-regulated IGF1 isoform expression, potentially relevant to oestrogen-sensitive tissues like the endometrium." (PMID 39796756, 2025). "Antibiotic treatment reduced the production of SCFAs by the gut microbiota, whereas exogenous administration of SCFAs was found to promote prostate cancer progression through elevation of insulin-like growth factor 1 (IGF-1) levels." (PMID 41403642, 2025). "However, the clinical application of anabolic agents (e.g., GH/IGF-1 axis modulators) is significantly constrained by their potential tumor-promoting effects, necessitating rigorous benefit–risk assessment—particularly in hormone-sensitive malignancies (e.g., breast and prostate cancers)." (PMID 41487675, 2025). "Extensive research has revealed that that SCFAs play a regulatory role in the expression of human insulin-like growth factor-1 (IGF-1), a crucial hormone for bodily growth, yet a detrimental factor in prostate cancer." (PMID 39948481, 2025). "The nutrient-sensitive kinase mTORC1 is upregulated in nearly 100% of advanced human prostate cancers, and this kinase is activated by leucine, insulin, IGF-1, and glucose." (PMID 39941741, 2025). "IGF-1 contributes to the development of prostate cancer by stimulating cell proliferation and by inhibiting apoptosis." (PMID 41108364, 2025). "Correlation of PSA, insulin, IGF-1 and testosterone with other influencing parameters in prostate cancer group." (PMID 39781138, 2024). "Previously, we found low-carbohydrate diets slowed prostate cancer (PC) growth and increased survival vs. a Western diet in mice, by inhibiting the insulin/IGF-1 axis." (PMID 38082056, 2024).
prostate carcinoma (continued). "In this study, we observed significantly elevated insulin and insulin-like growth factor-1 levels in both benign prostatic hyperplasia and prostate cancer groups." (PMID 39781138, 2024). "We have noted a previous, randomised phase II trial of IGF‐1 blockade for the treatment of advanced prostate cancer." (PMID 38515274, 2024). "Lycopene can also exert its anti‐proliferative effects on prostate cancer cells through its antioxidant properties and suppression of androgen and IGF‐1 signalling pathways." (PMID 38515274, 2024). "Each unit increase in serum insulin-like growth factor-1 levels increases the chances of prostate cancer by 6% (OR: 1.06; 95% CI; p<0.004)." (PMID 39781138, 2024). "IGF‐1 signalling is a major survival pathway for cancer cells and is involved in the development of castration‐resistant prostate cancer and docetaxel resistance via interaction with androgen signalling." (PMID 38515274, 2024). "SCFAs can also stimulate the production of insulin‐like growth factor 1 (IGF1) to promote the growth of prostate cancer by activating the MAPK and PI3K signalling." (PMID 39568157, 2024). "In line with our findings, ZEB1 has been confirmed as a key transcriptional regulator of EMT, and its expression was elevated by IGF‐1 in prostate cancer cells." (PMID 36988055, 2023). "SCFAs regulate prostate cancer growth via systemic and local prostate insulin-like growth factor-1 (IGF-1)." (PMID 37441422, 2023). "Evaluation of IGF-1 inhibition as a novel route to radiosensitization of prostate cancers that express high total- or cytoplasmic- IGF-1R." (PMID 36831629, 2023). "Dairy consumption increases blood levels of insulin-like growth factor-1 (IGF-1), which is suggested to be a risk factor for prostate cancer." (PMID 38187795, 2023). "IGF-1 is also secreted from prostate cancer cells in an autocrine manner and enhances prostate cancer growth via the mitogen-activated protein kinase (MAPK) and phosphatidylinositol-3 kinase (PI3K) signaling pathways." (PMID 37441422, 2023). "IGF-1 stimulated prostate cancer growth via the mitogen-activated protein kinase (MAPK) and phosphatidylinositol-3 kinase (PI3K) signaling pathways." (PMID 36900168, 2023). "Significantly, VCAM1 expression was elevated in vascular endothelial cells under the stimulation of IL-17 and insulin/IGF1, which strengthened the adhesion between PCa cells and vascular endothelial cells and promoted prostate cancer metastasis." (PMID 37494663, 2023). "In the Pten-knockout prostate cancer mouse model, SCFAs also stimulated the production of IGF-1 in prostate tumors and other organs, such as liver, contributing to augmented prostate cancer growth." (PMID 36900168, 2023). "Another study proposed an innovative perspective, that the intestinal bacteria, acting through short-chain fatty acids, regulate systemic and local prostate IGF1 in the host, which can promote the proliferation of prostate cancer cells." (PMID 37705744, 2023). "To further explore the correlation of IGFBP3 status to IGF1 activation in human prostate cancer samples, we employed HiSeq RNA sequencing data from TCGA (The Cancer Genome Atlas) and GEO (GSE197780) datasets." (PMID 36323713, 2022). "Gut microbiota-derived SCFA upregulated local and systemic insulin-like growth factor-1 (IGF-1), which favored prostate cancer development." (PMID 35280689, 2022). "Correlations between altered androgen, IGF1, and Wnt/β-catenin signaling are also identified in human prostate cancer samples, uncovering a dynamic regulatory loop initiated by the AR through prostate cancer development." (PMID 35902588, 2022). "Androgen-resistant PC3 and DU145 and androgen-sensitive LNCaP and VCaP prostate cancer cells were stimulated with IGF-1 and tumor growth (all cell lines), adhesion and chemotaxis (PC3, DU145) were determined." (PMID 35053528, 2022).
prostate carcinoma (continued). "Early studies strongly support that periprostatic adipose tissue, particularly under metabolic syndrome-associated inflammation, is a key player in the development of prostate cancer, through the IGF-1 axis, adipokines, and sex hormones." (PMID 36017326, 2022). "Here the authors show that AR activation in a subpopulation of prostatic progenitor cells can initiate prostatic intraepithelial neoplasia formation and promotes prostate cancer development through activation of IGF1 and Wnt/β-catenin signalling pathways." (PMID 35902588, 2022). "The correlations in co-occurrences of altered androgen, IGF1, and Wnt/β-catenin signaling pathways were further identified in human prostate cancer samples." (PMID 35902588, 2022). "Oral supplementation of SCFAs to mice fed a HFD who received antibiotic resulted in increased serum IGF-1 levels and promoted prostate cancer growth." (PMID 35370981, 2022). "The present investigation employing prostate cancer cell lines in vitro point to a dual role of IGF-1." (PMID 35053528, 2022). "Emerging evidence has shown a prominent role of IGF1/IGF1R signaling activation in inducing prostate cancer development and progression in both mouse models and clinical studies." (PMID 36323713, 2022). "In prostate cancer cells, IGF-1 upregulates expression of transcriptional factor ZEB1 and also increases expression of fibronectin and N-cadherin." (PMID 36361979, 2022). "In human prostate cancer, it was recently suggested that periprostatic adipose tissue promotes resistance to docetaxel by paracrine IGF-1 upregulation, further supporting its role in the tumor microenvironment." (PMID 35954439, 2022). "Prostate cancer growth and invasion are thus controlled by a fine-tuned network between IGF-1 driven integrin-FAK signaling and the Akt-mTOR pathway." (PMID 35053528, 2022). "IGF-1 is an essential hormone for physical growth and has various effects in several diseases, especially prostate cancer, where it functions as an exacerbating factor." (PMID 35370981, 2022). "Prostate cancer has long been recognized as a hormone-related cancer; previous studies have reported associations between various hormones (e.g., insulin-like growth factor 1 (IGF-1), testosterone) and the risk of prostate cancer." (PMID 35144655, 2022). "The addition of black tea polyphenols was found to block the progression of IGF-1-induced cell growth into the S-phase of the cell cycle at a dose of 40 mg/ml in prostate cancer." (PMID 36172282, 2022). "Although the relevance of IGF-1 as a prognostic biomarker in prostate cancer patients has been demonstrated in several cohort studies, its mode of action remains unsettled." (PMID 35053528, 2022). "In hepatocellular carcinoma, EMT is driven by IGF1-induced activation of the transcription factor STAT5, while in prostate cancer cells, IGF1 stimulation up-regulates ZEB1, a zinc finger homeodomain transcriptional repressor." (PMID 33673232, 2021). "The present study demonstrated that diosmetin is able to effectively alter the AKT and PKCα signaling cascade in prostate cancer cells, which can be activated by both IGF-1 and IL-6." (PMID 34682865, 2021). "The expression of Rictor, phosphorylation of Rictor (Thr-1135), AKT (Ser-473) and PKCα (Ser-657) were all increased after IGF-1 and IL-6 treatment in both prostate cancer cell lines and in RWPE1 cells." (PMID 34682865, 2021). "Prostate cancer cell lines LNCaP (androgen responsive) and PC-3 (androgen refractory) were next treated with IGF-1 at a range of doses and for a range of time points." (PMID 34682865, 2021). "Among the currently known growth signals, insulin-like growth factor (IGF)-1 and IL-6 have been previously studied for their roles in prostate cancer." (PMID 34682865, 2021). "When prostate cancers become unresponsive to androgens, upregulation of insulin-like growth factor 1 (IGF-1) is often detected." (PMID 33922595, 2021).
prostate carcinoma (continued). "Over expression of IGF-1/IGF-1R has been found to result in the initiation of prostate cancer with the PI3/Akt and Ras/Raf/MEK/MAPK being the major pathways associated with the activation of the same." (PMID 35095521, 2021). "IGF-1 has been shown to initiate growth response in both androgen dependent and androgen-independent prostate cancer cell lines." (PMID 33816477, 2021). "One study suggested a link between fat intake and prostate cancer involving IGF‐1, insulin, or leptin." (PMID 34606688, 2021). "In normal prostate cells IGF-1 maintained differentiated cellular characteristics, however in prostate cancer cells it induced a mesenchymal phenotype." (PMID 33816477, 2021). "It is noteworthy that IGF1 levels were measured an average of seven years before the diagnosis of prostate cancer." (PMID 33182502, 2020). "According to the reported results, the expression of AR and IGF-1 in prostate cancer decreased as the expression of AMACR decreased." (PMID 32760737, 2020). "Over the years, serum levels of IGF-1, IGF-2, and IGFBP3 have been evaluated as predictive biomarkers for breast and prostate cancers, with elevated IGF-1 levels being assigned as a risk factor for prostate cancer." (PMID 32226608, 2020). "Later, the rs1520220 C allele was widely discussed in increasing different types of cancer risks and IGF1 serum levels, such as prostate cancer, ovarian cancer, stomach cancer, and more." (PMID 32150843, 2020). "Higher serum levels of IGF-1 are associated with increased all-cause mortality and PCSM in men with advanced prostate cancer." (PMID 32056047, 2020). "These detrimental effects are also seen in studies of prostate cancer xenografts, where increased expression of IGF-1 and its receptor by prostate cancer cells results in tumour progression to castrate resistant prostate cancer (CRPC)." (PMID 32056047, 2020). "For example, the ORs per SD increase of genetically predicted IGF‐1 levels were 1.13 (95% CI 1.03‐1.25; P = .01) for colorectal cancer and 1.10 (95% CI 1.00‐1.21; P = .05) for prostate cancer." (PMID 32717139, 2020). "Survivin expression has also been shown to increase with exposure to insulin-like growth factor-1 (IGF-1) in prostate cancer." (PMID 30729097, 2019). "In prostate cancer, IGF-1 induced survivin expression via activation of the mTOR/p70S6K axis, leading to increased translation of pre-existing survivin mRNA; this process was inhibited by introduction of a p70S6K siRNA and by the mTOR inhibitor rapamycin." (PMID 30729097, 2019). "Men with high serum IGF‐1 were more likely to have prostate cancer (highest vs lowest quartile, odds ratio [OR] = 3.35; Ptrend < 0.001)." (PMID 29992746, 2018). "A previous study where subcutaneous tumors had been generated in SCID mice using PC-3 prostate cancer cells (advanced prostate cancer), resulted in the interesting observation that, 1 week after palpable tumor detection, IGF-1 Ec was moderately expressed." (PMID 30134795, 2018). "IGF-1 (mature and isoforms) expression was examined by qRT-PCR, both in prostate cancer cells co-incubated with cells of the immune response (IR) and in tumors." (PMID 30134795, 2018). "The potential roles of IGFs and IGFBPs in mediating cell movement and migration have been studied more so in cancer cells than in stromal stem cells, for, for example, degradation of IGF‐1/IGFBP3 complex by MMP‐9‐triggered prostate cancer cell migration." (PMID 29321953, 2018). "Activated osteoclasts resorb bone releasing growth factors including TGF-beta and IGF-1 which further stimulate prostate cancer growth." (PMID 29867053, 2018). "BA decreases serum PSA levels by 88%, inhibits the LNCap tumour growth by 38% and reduces insulin-like growth factor-1 in nude mice injected with human LNCap prostate cancer cells." (PMID 28059072, 2017).